MIR4650-1 (microRNA 4650-1)
Synonyms: hsa-mir-4650-1
Gene: MicroRNA gene on chromosome 7 (67,114,322 to 67,114,397, reverse strand). Ensembl gene ENSG00000266525.
Homologues: Paralogues in human: MIR4650-2 (100% identical).